ADM (adrenomedullin)
Diseases named in the same sentence as ADM in open-access papers (continued):
Sharing a sentence is not in itself a finding about the gene and the disease.
Sepsis (continued). "Adrenomedullin (ADM) is a 52-amino acid peptide hormone that was originally isolated from pheochromocytoma cells and has emerged as a promising biomarker in the diagnosis of sepsis in humans." (PMID 39518777, 2024). "Moreover, previous data on ADM expression in patients with sepsis had revealed a correlation between reduced HIF1A levels and lower ADM expression in peripheral leukocytes." (PMID 38714572, 2024). "The non-neutralizing anti-Adrenomedullin antibody Adrecizumab has shown promising results in animal models of systemic inflammation and sepsis, and in a phase II human trial." (PMID 36836567, 2023). "Adrenomedullin (ADM) is a peptide produced by multiple tissues in response to an infective stimulus, leading to a rapid increase in its plasma concentration, with apparently beneficial effects on the pathophysiology of sepsis." (PMID 35327521, 2022). "Although observational, this study first provided the first suggestion that bio-ADM and DPP3 might represent two distinct and partly independent pathophysiological mechanisms involved in the development of organ dysfunction during sepsis." (PMID 36530868, 2022). "In preclinical sepsis models, Adrecizumab, a non-neutralizing monoclonal anti-ADM antibody, improved endothelial barrier function and reduced organ failure, as well as mortality." (PMID 36530868, 2022). "Further, modulation of the ADM hormonal system using antibodies against a non-ligand binding site of ADM has been suggested a potential therapy in sepsis." (PMID 33148300, 2020). "Adrenomedullin (ADM) regulates vascular tone and endothelial permeability during sepsis." (PMID 30583748, 2018). "ADM, along with ANP and BNP, may participate in initiating the hyperdynamic response during the early stages of sepsis because of their similar physiological functions, in agreement with the literature." (PMID 26880865, 2016). "In summary, with the physiological roles of ADM taken together, our study shows that ADM, along with ANP and BNP, may participate in initiating the hyperdynamic response during the early stages of sepsis in uroseptic patients." (PMID 26880865, 2016). "In this first issue of Intensive Care Medicine Experimental, two related studies describe the effects of antibodies directed against adrenomedullin (ADM), a vasoactive peptide that is released from various tissues during systemic inflammation, in murine sepsis." (PMID 26266901, 2014). "Our results indicate that complete inhibition of ADM agonist activity during sepsis is not very efficacious, if at all, to improve survival." (PMID 26266791, 2013). "Not surprisingly, serum levels of ADM were shown to be increased in sepsis." (PMID 16356231, 2005). "Additionally, ADM as a small peptide is prone to proteolytic degradation and - as plasma protease activities increase and vary in sepsis patients - it might not be an ideal drug structure by concept." (PMID 26266791, 2013). "Thus, it is not surprising that serum ADM levels are increased in sepsis." (PMID 16805922, 2006). "Top ranked hits included FAM20A, PPARG, ADM and ARG1, many of which are commonly expressed in both SIRS and sepsis disease groups relative to controls and are non-specific." (PMID 38332914, 2023).
heart failure (36 papers, 2010 to 2025). Inability of the heart to pump blood at an adequate rate to meet tissue metabolic requirements. "Elevated ADM levels in heart failure are associated with the severity of the condition and serve as a reliable indicator of lingering congestion in patients experiencing acute decompensated heart failure." (PMID 39432214, 2024). "Hypertension, heart failure, and renal failure are associated with increased adrenomedullin levels in adults, with evidence of increased MR-proADM expression in pediatric heart failure." (PMID 36239515, 2022). "Several studies have analysed the role of adrenomedullin in heart failure in adults, which is linked to cardiac remodeling under stress." (PMID 36010070, 2022). "Heart failure is associated with an increased risk of atrial fibrillation (AF), but the effects of adrenomedullin on atrial arrhythmogenesis remain unclear." (PMID 36430541, 2022). "Adrenomedullin, a biomarker of cardiac injury, is crucial in assessing the severity of heart failure and regulating cardiovascular homeostasis." (PMID 39325159, 2025). "Atrial natriuretic peptide (ANP) and adrenomedullin (ADM) are additional biomarkers of clinical importance for the treatment of heart failure (HF)." (PMID 40129519, 2025). "Plasma adrenomedullin (ADM) concentrations rise proportionately with the severity of heart failure, evident in both diastolic and systolic heart failure cases." (PMID 39432214, 2024). "The secretion of ADM is primarily triggered by an excessive volume of fluid in the body, making it a potential biomarker for tissue congestion in heart failure." (PMID 39432214, 2024). "Since high ADM plasma levels are protective, its degrading enzyme, the neutral endopeptidase neprilysin, has been recognized as new target for heart failure patients." (PMID 38999939, 2024). "ADM and AVP both reflect neurohumoral activation, a hallmark of heart failure, whereas ANP is a biomarker of myocardial stretching, closely resembling brain natriuretic peptide, a well-established marker of congestive heart failure." (PMID 35267617, 2022). "Here, we show that circulating levels of ST2, an established biomarker in heart failure, and adrenomedullin, a vasodilator peptide known to reflect several aspects of cardiovascular status, strongly correlate with survival in small cell lung cancer." (PMID 35267617, 2022). "ET-1 and adrenomedullin (ADM) levels in the blood are more significant in people with heart failure than in healthy individuals." (PMID 36264449, 2022). "It has been demonstrated that serum ADM levels were elevated in heart failure (HF) patients, and its change in response to the pathophysiologic changes of HF." (PMID 35355972, 2022). "In the results, the authors found elevated ADM concentrations in the subsequent stages of heart failure and that the left ventricular ejection fraction inversely correlated with plasma ADM concentrations." (PMID 33540505, 2021). "Strong evidence supports links between plasma proteins used in the construction of GrimAge and various age-related conditions: ADM levels are increased in individuals with hypertension and heart failure." (PMID 30669119, 2019). "Pharmacological application of adrenomedullin has shown protective effects in models of renal or heart failure." (PMID 24465926, 2014). "Whereas adrenomedullin has consistently been reported as a biomarker in a variety of diseases among them coronary artery disease and heart failure, little is known about the peptide in AF." (PMID 25401728, 2014). "Plasma ADM level is elevated in hypertension, heart failure, acute myocardial infarction, atherosclerosis and type 2 diabetes." (PMID 23936408, 2013). "This type of heart failure includes cardiac output elevation compared with metabolic demand and a decrease in systemic vascular resistance mediated by the peripheral vasodilator adrenomedullin." (PMID 37835772, 2023).
heart failure (continued). "In addition to NT-proBNP, we also identified another heart failure-related biomarker, adrenomedullin, which has previously been found to play a pathophysiological role in kidney disease." (PMID 37407978, 2023). "Plasma levels of ADM are elevated in cardiovascular diseases such as heart failure, hypertension, and septic shock, where ADM may play protective roles through its biological activities." (PMID 36836567, 2023). "Similarly other biomarkers such as Mid-regional pro-Atrial Natriuretic Peptide, ST2, C-Terminal pro-endothelin 1, Mid-regional pro-Adrenomedullin and copeptin all provide incremental information in predicting death and heart failure." (PMID 20529285, 2010). "It was demonstrated that adrenomedullin (ADM) and endothelin-1 (ET-1) contribute to the alterations in systemic vascular resistance and that ADM may act to improve left ventricular function during static exercise, especially in patients with heart failure and healthy older men." (PMID 23487485, 2012). "Cardiovascular biomarkers (pro-ADM, pro-ANP) were shown to decrease in patients with heart failure, and limited literature is available on the efficacy of exercise on Copeptin." (PMID 31316451, 2019). "Adrenomedullin (ADM) represents a vasodilatory peptide hormone of 52 amino acids, which is released in several disease states such as heart failure, renal failure, respiratory failure, liver cirrhosis, cancer, as well as infectious diseases incl." (PMID 28820494, 2017). "Bio-ADM: Bioactive adrenomedullin; CA125: Carbohydrate antigen 125; eGFR: Estimated glomerular filtration rate; HF: Heart failure; IGFBP7: Insulin-like growth factor binding protein 7; sST2: Soluble Suppression of Tumorigenicity-2; TIMP-2: Tissue inhibitor of metalloproteinases-2." (PMID 41157213, 2025). "Searches were performed in PubMed, Scopus, and Web of Science using combinations of keywords such as “cardiorenal syndrome,” “biomarkers,” “heart failure,” “acute kidney injury,” “chronic kidney disease,” and specific marker names (e.g., NGAL, KIM-1, cystatin C, CA125, bio-ADM, FGF-23, etc.)." (PMID 41157213, 2025). "In individuals without heart failure, ADM is present in low concentrations, typically around 13 pg/mL." (PMID 39432214, 2024). "Similarly, MSCs overexpressing adrenomedullin (ADM) enhanced heart function and increased cell survival in a rat model of heart failure." (PMID 37434264, 2023). "The levels of both CNP and adrenomedullin are increased in proportion to the severity of heart failure; however, the magnitude of that increase is modest, and plasma CNP and adrenomedullin often only modestly correlate with measures of cardiac function, such as LVEF." (PMID 36101368, 2022). "Exogenous administration of ADM and CGRP peptides or their gene delivery is a new preventive and therapeutic strategy for cardiovascular diseases such as hypertension, myocardial ischemia, heart failure, and renal failure." (PMID 34437633, 2021). "Furthermore, because both CNP and adrenomedullin mRNA are strongly induced in vascular endothelial cells by cytokines, such as tumor necrosis factor-α or interleukin-1β, increased plasma CNP levels may reflect a chronic inflammatory state in heart failure." (PMID 36101368, 2022).
Hypertension (35 papers, 2013 to 2025). The presence of chronic increased pressure in the systemic arterial system. "Coexistence of T2DM and hypertension can also be explained genetically, since there is evidence indicating that variants of angiotensinogen and adrenomedullin gene are associated with both conditions." (PMID 33021758, 2021). "Significant differences in the frequencies of the ADM alleles were observed in boys: NBP vs. hypertension (P = 0.027), and in girls: NBP vs. prehypertension (P = 0.016) (data not shown)." (PMID 31048758, 2019). "According to the univariate logistic regression, the additive model fitted best for the association of ADM rs7129220 with prehypertension in girls (OR 2.58, CI 95% 1.15–5.81) and hypertension in boys (OR 1.93, CI 95% 1.09–3.43)." (PMID 31048758, 2019). "The present study investigated the associations of the ADM gene polymorphism (rs7129220) with high blood pressure among Lithuanian adolescents aged 12–15 years." (PMID 31048758, 2019). "In conclusion, our results revealed an association between NLRP6/AVR and ADM loci and hypertension susceptibility in a northern Sardinian population, primarily affecting male essential hypertension." (PMID 24147025, 2013). "To assess the possible association of NLRP6/AVR and ADM with essential hypertension in our Sardinian cohort, we examined single-point associations between NLRP6/AVR and ADM SNPs with hypertension susceptibility." (PMID 24147025, 2013). "Here, we present evidence suggesting that the NLRP6/AVR and ADM loci contribute to hypertension susceptibility in a Sardinian population." (PMID 24147025, 2013). "Our results revealed an association between NLRP6/AVR and ADM loci with male essential hypertension, suggesting the existence of sex-specific NLRP6/AVR and ADM variants affecting male susceptibility to essential hypertension." (PMID 24147025, 2013). "For ADM, sex-specific analysis showed a significant association between rs4444073C, with increased susceptibility to essential hypertension only in the male population (P = 0.006; OR = 1.44 [1.13–1.84])." (PMID 24147025, 2013). "Similar number of DEGs caused by aging and hypertension were identified, and the common alteration mainly reflected in the myosin-interacting protein, hydroxytryptamine receptor, gap junction protein, C-X3-C motif chemokine ligand, and adrenomedullin." (PMID 36313372, 2022). "In humans, the ADM gene is located at chromosome 11, and genetic variations in the ADM gene may determine blood pressure levels and the risk for hypertension; however data from various studies are inconsistent." (PMID 31048758, 2019). "Finally, we analysed associations between high blood pressure and the ADM polymorphism by inheritance models." (PMID 31048758, 2019). "Among new identified loci for hypertension there are genes encoding ADM and CACNB2." (PMID 25313554, 2014). "Furthermore, ADM concentrations strongly correlated with serum creatinine levels which may have resulted from kidney damage caused by hypertension." (PMID 33540505, 2021). "Moreover, recent studies have implicated ADM in hypertension pathogenesis in humans." (PMID 24147025, 2013). "In addition, the ADM SNP rs4399321 utilized in our study has been reported to be associated with proteinuria in subjects with essential hypertension and with BP levels in normotensive subjects in a Chinese population supporting a regulatory role for ADM in blood pressure homeostasis in humans." (PMID 24147025, 2013). "Ali reported that the ADM expression levels were highly elevated in the plasma of hypertension patients." (PMID 36978012, 2023). "Notable observations revealed a significantly elevated plasma level of ADM among individuals diagnosed with essential hypertension in comparison to normotensive persons." (PMID 38069140, 2023). "Here, we found the significant association of ADM, EDN1, ANGPTL4, USP8, NFIL3, MSR1, and CEBPD genes with hypertension." (PMID 35205232, 2022).
Hypertension (continued). "ADD1, ADM, and ADRB2 were included for the NGS analysis for detecting variants related to hypertension." (PMID 35999587, 2022). "This suggests a potential value for measuring ADM levels in hypertension, although the detailed relationship between plasma ADM levels and blood pressure is yet to be understood." (PMID 35628490, 2022). "From 50 DEGs, we ranked 7 hypertension-related genes (p-value < 0.05): ADM, ANGPTL4, USP8, EDN, NFIL3, MSR1, and CEBPD." (PMID 35205232, 2022). "Specifically, ADM is a vasodilator, and its insufficiency is associated with the pathogenesis of CVD, hypertension, and diabetes." (PMID 34083497, 2021). "For example, in CKD patients, levels of adrenomedullin have been found to be high, although its role in hypertension is uncertain." (PMID 33628672, 2021). "Plasma ADM levels are increased in patients with high blood pressure, particularly in those with uncontrolled hypertension and consequently left ventricular hypertrophy." (PMID 33540505, 2021). "Data from studies have shown that plasma ADM level increases in patients with cardiovascular diseases, including hypertension, heart failure, and chronic renal failure." (PMID 31048758, 2019). "Studies have shown that in humans, plasma levels of ADM are higher in patients with various cardiovascular diseases, including hypertension, and correlate with disease severity." (PMID 31048758, 2019). "For evaluation of genotype effect on the risk of hypertension, four SNPs were chosen: two SNPs (AGT and ACE) related to renin-angiotensin-aldosterone system and other two SNPs (ADM and CACNB2) newly identified in genome-wide association studies." (PMID 25313554, 2014). "ADM is a 52-amino acid peptide and its plasma level is elevated in many clinical conditions including hypertension, septic shock, renal failure and in type 2 diabetes." (PMID 23936408, 2013). "Specific ADM and NLRP6/AVR variants affecting susceptibility to high blood pressure require further investigation." (PMID 24147025, 2013). "ADM levels in the tissues and plasma are elevated as a response to pathologic conditions such as hypertension, tissue hypoxia or hypervolemia, and cytokines (e.g. tumor necrosis factor (TNF)-α, and interleukin (IL)-1) trigger release of ADM in vascular endothelial and smooth muscle cells." (PMID 39245743, 2024). "The role of the ADM gene mechanism was found in clinical research related to hypertension." (PMID 35205232, 2022). "However, in patients with hypertension, ADM elevation directly correlates with the stages of hypertension as defined by the World Health Organization (WHO), as well as with the severity of target organ damage." (PMID 35628490, 2022). "First—plasma ADM level was elevated before the development of hypertension." (PMID 33540505, 2021). "The increase of plasma ADM level was more prominent in kidney failure than in hypertension." (PMID 33540505, 2021). "Role of adrenomedullin in EPO-induced hypertension is uncertain." (PMID 33628672, 2021). "The results revealed an increase of plasma ADM concentration in whole studied population then in healthy individuals and what is even more interesting, it was higher in subjects with kidney failure comparing to those with hypertension." (PMID 33540505, 2021). "Vasopressin, endothelin and adrenomedullin are vasoactive peptides that regulate vascular tone and might play a role in hypertensive diseases." (PMID 24465926, 2014). "Therefore, reduced levels of adrenomedullin may be consistent with the development of hypertension in these patients." (PMID 40558670, 2025). "Therefore, this research was designed to explore whether ADM involved the hypertension and cardiac inflammation and oxidative stress of OH rats induced by a high-fat diet (HFD)." (PMID 35745637, 2022). "In another one, ADM was isolated from cardiomyocytes and cardiac fibroblasts, which may suggest its involvement in the regulation of myocardial hypertrophy and remodelling secondary to hypertension." (PMID 33540505, 2021).
Hypertension (continued). "Besides, NLRP6 inflammasome dysfunctions have been associated with adrenomedullin (ADM) loci and male essential hypertension, which suggests that NLRP6 inflammasome and potentially other NLRP inflammasome dysregulation promote pathogenesis of essential hypertension." (PMID 38644450, 2024). "ADM, EDN1, ANGPTL4, NFIL3, MSR1, CEBPD, and USP8, based on their FDR values (<0.05, p-values (≤0.05)), were the top DEGs for hypertension." (PMID 35205232, 2022). "Based on their disease–gene associations, these biomarkers are involved in vascular inflammation (HO-1, LPL, PAPPA, ADAMTS13, ADM, PGF, and GDF-2), hypertension, and arterial disease (PAPPA, ADAMTS13, ADM, and PGF)." (PMID 35327515, 2022). "Our search revealed both known KDs showing connections to hypertension or relevant conditions in one or more types of studies (99 KDs; such as GNAS, SLC2A3, IRS1, ADM, and SERPINE1) and relatively novel KDs in BP studies (such as SPTBN1 and GNB1)." (PMID 30931314, 2019). "(MR-pro)ADM levels are increased in cardiovascular disease (CVD) and hypertension." (PMID 39469923, 2024). "This study aimed to determine whether adrenomedullin (ADM, 7.2 μg/kg/day, ip), an important endogenous active peptide, has a protective role in cardiac remodeling and function in obesity-related hypertension (OH) rats." (PMID 35745637, 2022). "However, in contrast to our study, the author did not assess adrenomedullin levels before 20 weeks of pregnancy in a population of women who had developed hypertension during pregnancy." (PMID 39682578, 2024).